VWF (von Willebrand factor)
Diseases named in the same sentence as VWF in open-access papers (continued):
Sharing a sentence is not in itself a finding about the gene and the disease.
tumor (continued). "In tumor tissue, we performed immunohistochemistry and confirmed the findings by western blot, to determine the effects of progesterone on markers of tumor proliferation (PCNA), angiogenesis (VWF), and apoptosis (cleaved caspase-3)." (PMID 30700763, 2019). "We examined the relationship between the VWF:Ag/ADAMTS13:AC ratio and serum tumor markers, such as AFP, DCP, and AFP-L3%." (PMID 31638892, 2019). "The tumours presented as bloody lesions and stained positively for CD31 and vWF by immunohistochemistry." (PMID 29731980, 2018). "The expression of markers of hypoxia (HIF2α), angiogenesis (VEGF), tumor microvascularity (CD31, CD34, vWF, CD105), and proliferation (Ki-67) were assessed immunohistochemically (IHC)." (PMID 29662659, 2018). "The tumor cells also showed increased cellular survival by the overexpression of survivin, HSP-70, 14–3-3, and angiogenesis-related proteins, e.g., HIF, vWF, CMG2, and bFGF, compared to SSC-1." (PMID 28789700, 2017). "We observed that vWF expression in HUVECs was increased by A549 tumor cell-conditioned medium, suggesting that LAC cells secrete a factor or combination of factors that upregulate vWF." (PMID 29299165, 2017). "We performed immunofluorescence staining on tumor samples as well as normal brain and bone control tissues using antibodies against the endothelial marker CD31 and VWF." (PMID 28035064, 2017). "Tissue analysis for our patient showed the tumor cells stained positive for CD31, CD34, CD68, S-100, vWF, and Ki-67." (PMID 27651973, 2016). "The integration from our omics-based research provides a four molecular pathway foundation (ANXA2/HMGA1/POU3F1; NFRSF13/GSN; TMOD3/RAI14/VWF; and PLAT/PLAU) behind HO-1 regulation of tumor cytoskeletal cell compartments." (PMID 28032857, 2016). "Because tumor cell-secreted VEGF-A is a mediator of EC activation in addition to thrombin, VWF fibers were examined in tumor tissue." (PMID 27602496, 2016). "Most of the undifferentiated GC tumor tissues at late disease stage exhibited strong VEGF and VEGFR2 protein staining, which co-localized with the vWF protein staining pattern." (PMID 25886574, 2015). "Tumor sections stained with anti-CD31 and anti-vWF antibodies revealed that Oridonin inhibited new blood vessels as well as pruned preexisting tumor vessels." (PMID 25485753, 2014). "By quantifying the levels of immunohisto-chemical endothelial cell markers (vWF and CD31) on 4T1 primary tumor sections, we found a similar level of angiogenesis in tumors collected from animals treated and untreated with Debio 0719." (PMID 22200658, 2012). "In this study, using a xenograft mouse model and immunohistochemistry with anti-vWF and anti-CD31 antibodies, we demonstrated that harmine inhibited tumor growth with low side-effects by suppressing tumor angiogenesis." (PMID 23300602, 2012). "In general, the MVD has been quantified by immunohistochemical staining of tumor blood vessels with the use of antibodies, including CD31, CD34, von Willebrand Factor (vWF) or Factor VIII-related antigen (FVIII) and CD105." (PMID 24212960, 2011). "Blood vessels were examined by staining the tumor tissues by H&E, anti-CD31 antibody, and anti-vWF antibody." (PMID 18226269, 2008). "For that purpose, we double-stained human multi-tumor tissue microarrays with antibodies against IL-33 and CD31 or vWF." (PMID 18836528, 2008). "Traditionally, angiogenesis has been assessed using markers including von Willebrand factor (vWF), VE-cadherin (also known as cadherin-5) and PE-CAM (CD31), and has been found to be increased in tumour tissues compared with normal tissues." (PMID 16430777, 2006).
tumor (continued). "In contrast, a significant positive correlation was observed between VWF and CD8 + T cells (r = 0.258, p = 1.22 × 10−6), whereas there was a significant negative correlation between VWF and tumor purity (r = −0.159, p = 3.09 × 10−3)." (PMID 40699668, 2025). "TIMER2 immune association analysis showed a significant negative correlation between VWF and tumor purity (proportion of tumor cells in the tumor microenvironment) (r = −0.159, p = 3.09 × 10−3) and CD4 + T cells (r = −0.134, p = 1.28 × 10−2)." (PMID 40699668, 2025). "The interaction of vWF with normal stomach cell lines does not show specific staining to differentiate it from tumor cells." (PMID 39456895, 2024). "Both tumour were negative for both cytokeratins and von Willebrand factor, excluding an epithelial and endothelial origin respectively." (PMID 37525233, 2023). "And GAD1, NOS3, SERPINE1, and VWF protein levels were not significantly different in tumor and normal samples." (PMID 36860371, 2023). "High plasma VWF levels were a better biomarker for poor survival than the well-known tumor marker CEA (carcinoembryonic antigen) which was not significantly changed in accordance with advanced stage and poor prognosis." (PMID 35327035, 2022). "However, tumor cells expressing high levels of ADAM28, a novel VWF cleavage protease, displayed resistance to this VWF-induced apoptosis in vivo." (PMID 35327035, 2022). "Given the evidence that tumor cells are Lkb1-positive and strict EYFP expression in tumor ECs (identified by positive staining for vWF [vWF+]) in the lineage-tracking mice (Stk11ec (EYFP)−/−), we concluded a non-cell-autonomous effect of EC Stk11 deficiency on tumorigenesis or tumor suppression." (PMID 35115536, 2022). "From the rest of the tumor cells, the first parameter to differentiate ECs is a division through CD45−, as a pan-hematopoietic marker that combines with CD31, CD144 (VE-Cadherin), and vWF (von Willebrand Factor)." (PMID 35707536, 2022). "An immunofluorescence analysis on tumor tissue sections using the Von Willebrand Factor evidenced the complete absence of this endothelial marker in LSAA/HPUFA-fed mice, indicating the inhibited angiogenesis." (PMID 36613691, 2022). "In addition, VWF and PTEN were also found to share nine co-occurrent alterations in ILC, possibly working in tandem to promote tumour progression." (PMID 33571850, 2021). "Immunohistochemical staining for the endothelial marker von Willebrand factor (vWF) demonstrated that blood vessel formation was significantly reduced in BTG3-overexpressed tumors, thus supporting a negative regulatory role of BTG3 on tumor angiogenesis." (PMID 33311481, 2020). "DTs showed only a mild increase in the number of CD34-positive cells and no changes in VWF expression in comparison with PTs, which displayed a similar tumor size." (PMID 31803626, 2019). "The targets of aptamers actually in clinical trials are extracellular proteins (VEGF165, C5, PDGFβ, coagulation factor IXa, A1 domain of von Willebrand factor, thrombin, TFPI, CXCL12, CCL2, hepcidin peptide hormone), except nucleolin which is highly expressed at the surface of several tumor cells." (PMID 28635657, 2017). "The tumor cells of SSC-2 also showed increased cellular survival by the overexpression of survivin, HSP-70, 14-3-3, and the angiogenesis-related proteins HIF, vWF, CMG2, and bFGF compared to SSC-1." (PMID 28789700, 2017). "Taken together, the findings suggest a non-cell autonomous mechanism by which soluble tumor-derived factors contribute to elevated expression of vWF in the vasculature of tumors." (PMID 29299165, 2017). "Although the expression of six endothelial differentiation marker genes (PECAM1, vWF, FLT1, FLT4, KDR, CDH5) was significantly lower in normal and tumor ADSC, there was significantly greater expression of PDGFRB in ADSC when compared to BEC and NORMA1 MEC cells." (PMID 26968831, 2016).
tumor (continued). "Strikingly, when integrating the transcriptome under HO-1 modulation with the HO-1 interactome, a framework of four main molecular pathways arose as the foundation for the regulation of the tumor cell protrusive forces: ANXA2/HMGA1/POU3F1; NFRSF13/GSN; TMOD3/RAI14/VWF; PLAT/PLAU." (PMID 28032857, 2016). "Interestingly, multiple tumor-free distal organs exhibited hallmarks of malignancy-related VTE, including luminal VWF fibers, platelet-rich thrombi and vessel occlusions." (PMID 27602496, 2016). "However, the LMWH Tinzaparin with a higher molecular weight, inhibited tumor cell-secreted VEGF-A and abolished VWF release to the same extent as Bevacizumab." (PMID 27602496, 2016). "Platelet-tumor cell aggregates form through binding of platelet integrin αIIbβ3 to tumor cell integrin αvβ3 via RGD-containing proteins including fibrinogen, von Willebrand factor, and fibronectin, a process known as tumor cell-induced platelet aggregation (TCIPA)." (PMID 28105409, 2016). "Moreover, the recent discovery that VWF is an important modulator of angiogenesis and apoptosis provides an alternative, particularly intriguing, hypothesis to unify the mechanisms by which non-O blood group influences the onset of cardiovascular and neoplastic diseases." (PMID 25592962, 2015). "PNS treatment could decrease the expression of miR-18a in tumor and further down-regulate CD34 and vWF that led to angiogenesis inhibition in tumors, while an opposite activity by PNS on angiogenesis was observed in heart." (PMID 26305257, 2015). "Despite high expression of VEGF, VEGFR1, VEGFR2, bFGF, bFGFR, COX-2, von Willebrand factor, VE-cadherin, and laminin-5γ2 in these cells, VM does not depend on tumor angiogenesis." (PMID 25871476, 2015). "The GC tumor tissues also showed higher vWF mRNA and protein levels than the adjacent non-tumoral parenchyma." (PMID 25886574, 2015). "Staining for the sinusoidal endothelial cell marker CD31 indicated that there were a smaller number of blood vessels in the tumours made by miR-137 over-expressing MDA-MB-231 cells and furthermore the expression of vasculogenesis markers, VEGF and vWF were dramatically reduced." (PMID 26215676, 2015). "Correlation of presence or absence of tumor metastasis with lower or higher vWF cleaving respectively." (PMID 24213506, 2012). "The tumor cell-derived vasculogenic progenitors or vascular endothelial-like cells, which were lining on vessel walls, were determined by anti-human CD45, CD31, CD34, or VWF." (PMID 18286204, 2008). "More importantly, colocalization of KCa channels with vWF within microvessels was observed only within the tumor mass and not in normal brain." (PMID 17359538, 2007). "Repression of NTN4 and HYAL1 may promote cell migration and invasive growth, whereas BAI3, VWF, and EPB41L4B probably participate in angiogenesis, attachment of tumor cells to endothelial surfaces, or reflect vascular structures in the tumors." (PMID 17054779, 2006). "In one lung tissue pair, vWF levels in normal tissue were over 900-fold lower than in the tumor, such that normalization of HIP to vWF resulted in an apparent 30-fold increase in HIP in tumor compared to normal tissue." (PMID 15294024, 2004). "Tumour sections were stained with a pan-endothelial antibody (vWF) and vascularity was quantitated, without knowledge of the clinical details, by three methods: highest microvascular density; average microvascular density; and average microvascular volume." (PMID 9374385, 1997). "However, other cancer models showed an increase in metastatic deposits in the absence of VWF, due to VWF-mediated tumor cell apoptosis." (PMID 41536292, 2026). "Interestingly, most tumor cells in AS co-expressed PDPN and markers of blood vessel phenotypes (e.g., CD31, ERG, vWF), an unusual combination in normal vessels, suggesting their potential derivation from a common precursor of lymphatic and blood vascular endothelium." (PMID 40666093, 2025).
tumor (continued). "Compared with normal ECs, tumor-associated ECs display higher expression of the stem cell marker CD34 and the angiogenesis promoting markers CD61 (Integrin b3) and CD105 (Endoglin), and lower or absent expression of von Willebrand factor (vWF)." (PMID 38426109, 2024). "In addition to CD31, endothelial cells resulting from tumour cell transdifferentiation were reported to express various other markers that are generally considered to be vascular endothelial cell-specific, such as CD34, vWF, and VE-cadherin." (PMID 36823554, 2023). "After neoadjuvant treatment, responders exhibited higher SELP and VWF expression in tumor than non-responders, and the main components of TU-HEV endothelial cells may attribute to high immune infiltration." (PMID 37537219, 2023). "Our results showed that xenograft tumors contained a proportion of the tubule-like structures composed of endothelial/glial phenotypic (vWF+/GFAP+) cells, suggesting that U118 cells could directly transdifferentiate into or fuse with endothelial cells to participate in tumor angiogenesis." (PMID 34660561, 2021). "In addition, it has also been found that VWF levels increased within the primary tumour microenvironment, but not at the distal metastatic site." (PMID 33571850, 2021). "Notably, the VWF-mediated apoptotic effect appears to be specific to tumour cells, as VWF did not induce cell death in non-neoplastic cell lines examined." (PMID 33571850, 2021). "We showed that the expression of proteins specific to ECs (ACE+, VWF+), their differentiation (CD31+, CD 133+, CD105+, CD34-), their adhesion properties (ICAM-1+, VCAM-1+, CD62-L+), and their barrier formation (ZO-1+) were all downregulated in tumor-derived ECs." (PMID 34445568, 2021). "Zyxin could affect tumour haemorrhaging and growth because it has been shown to regulate the exocytosis of endothelial Weibel–Palade body (WPB) and the secretion of von Willebrand factor (vWF)." (PMID 33573141, 2021). "Previous studies have suggested that VEGF plays an important role in tumor extravasation and immune evasion through activation of the PLC/PKC/MAPK pathway and by promoting endothelial cells to secrete prothrombic mediators like von Willebrand factor (vWF) and P-selectin." (PMID 33807778, 2021). "Whereas, vWF was only found around EC in the adjacent non-cancerous tissues (non-tumor)." (PMID 30279208, 2018). "However, vWF has been reported to exert an anti-tumor effect, independent of its role in hemostasis." (PMID 29299165, 2017). "Moreover, VWF fibers promoted the formation of in vivo lung metastases in a mouse model for hematogenous tumor dissemination, but they exhibited no detectable effects on lymphatic metastasis." (PMID 27602496, 2016). "Thus, this study emphasizes a direct role of EC activation and VWF in triggering thrombosis in cancer patients already in a limited tumor stage (lymph node metastases, but no hematogenous tumor spread)." (PMID 27602496, 2016). "However, we have also become aware that VWF has a more versatile character than previously thought, given its potential role in various non-hemostatic processes, like intimal thickening, tumor cell apoptosis and inflammatory processes." (PMID 23936617, 2013). "However, in high-generation xenografts, staining for host nestin highlighted all tumor blood vessels with a sharply defined endothelium-specific labeling pattern comparable to labeling with the endothelial marker, von Willebrand factor (data not shown)." (PMID 22539956, 2012). "Both vWF and Tie2 protein expression patterns did not change during tumor growth." (PMID 22235379, 2011). "Interestingly, accumulations of VWF fibers were observed at similar extents in vessels in brain metastatic and perimetastatic regions, as well as in cerebral vessels in tumor-bearing mice without established brain metastasis, indicating a role in premetastatic niche formation." (PMID 37373202, 2023).
tumor (continued). "Therefore, elevated von Willebrand factor plasma levels, with an increased number of circulating EPCs, may adequately reflect treatment response, but not necessarily the tumour spread." (PMID 31731627, 2019). "Interestingly, vWF is now considered as a versatile multifunctional protein given its potential role in different non-hemostatic processes, like metastasis resistance and tumor cell apoptosis." (PMID 26306290, 2015). "A total of 127 unique non-overlapped (157 total) tumor endothelial cell over-expressed proteins identified from directly isolated kidney-associated ECs and those identified from ex-vivo cultured lung and colon tissues including known EC markers such as CD146, CD31, and VWF." (PMID 24236063, 2013). "Moreover, most vWF positive structures in the control tumors did not possess a lumen and may represent endothelial sprouts growing into the tumor." (PMID 17342201, 2007). "Last but not least, the Von Willebrand factor (VWF) can activate platelets to promote platelet aggregation and emboli formation via GPIb, promoting tumor metastasis." (PMID 35494001, 2022). "The ECs-related genes such as ANGPT2, CD34, LYVE1, VWF and PECAM1 were highly upregulated in the vascularized tumor tissue as compared to non-vascularized tissue due to the presence of BVs." (PMID 34754042, 2021). "Unlike numerous studies reporting that CD34 and VWF are involved in angiogenesis, our study shows that CD34 and VWF expression coincide with reduced tumor vasculature." (PMID 31803626, 2019). "Here, the overexpression of VWF was confirmed also by mRNA expression in GBM, compared not only to normal brain, but also to LGG and MNG, confirming its correlation with tumor malignancy and its potential use as prognostic factor." (PMID 29884885, 2018). "Neoangiogenesis has an important role in tumour growth and metastatization but the often used anti-factor-VIII-related antigen and anti-vWf do not discriminate between tumour neoangiogenesis and preexisting vasculature." (PMID 25236925, 2014). "We found that the majority of hybrid cell subpopulations in peripheral blood were not represented in the tumor tissue, for example, in the CRC samples B2 was defined by higher expression of CD45, VWF, and pAKT and B7 was defined by high expression of CK8, αSMA, and Ki67." (PMID 38538742, 2024). "Interestingly, our proteomic analysis has uncovered three proteins that were present either in tumor ECM alone (COL10A1) or in tumor and adjacent mucosa (EFEMP2 and vWF) and were absent in most distant mucosa samples." (PMID 35340765, 2022). "All tumors showed positive reactivity for CD31 and vWF, and positive reactivity for Ki-67 antigen of MIB-1 clone was observed in the nuclei of the tumor cells, but no positive reactions were observed in the surrounding murine tissues such as the epidermal basal cells." (PMID 22839755, 2012). "For this purpose, tumor sections were stained for the luminal endothelial cell marker podocalyxin, that we found to be the most suitable for automated vessel density quantification (this marker was validated by CD31 and von Willebrand Factor co-stainings, data not shown)." (PMID 30165893, 2018). "Interestingly, examination of tumor-driven vascularization in xenografts revealed a marked reduction of blood vessel density, as determined by reduced immunoreactivity of desmin and von Willebrand Factor VIII (vWF) (data not shown)." (PMID 29100402, 2017). "Indeed, while these tumours showed high levels of H-RAS expression in comparison to adjacent normal tissue and were immunoreactive for the common mesenchymal marker VIMENTIN, the tumour cells did not stain for lineage markers including CD31, vWF, DESMIN, SMA, MYOD1 or MYOGENIN (last column)." (PMID 29731980, 2018). "However, in all tumor samples we observed some cells that only express VWF but not CD31, (shown by white arrows) supporting their non-endothelial origin; this result is consistent with our hypothesis that these tumor cells acquired VWF expression." (PMID 28035064, 2017).